BST1 (bone marrow stromal cell antigen 1)
Description:
Catalyzes both the synthesis of cyclic ADP-beta-D-ribose (cADPR) from NAD(+), and its hydrolysis to ADP-D-ribose (ADPR). Cyclic ADPR is known to serve as an endogenous second messenger that elicits calcium release from intracellular stores, and thus regulates the mobilization of intracellular calcium (Probable). May be involved in pre-B-cell growth (Probable).
Synonyms: BST-1; CD157; cADPR2
Tractability: Small molecule: a structure with a bound ligand is known; it has a high-quality binding pocket. Antibody: its Gene Ontology location is reachable by antibodies, with high confidence; UniProt places it where antibodies can reach, with medium confidence; UniProt predicts a signal peptide or a membrane-spanning region. PROTAC: its protein half-life has been measured.
Target class: Enzyme; Hydrolase
Gene: Protein-coding gene on chromosome 4 (15,703,000 to 15,775,614, forward strand). Ensembl gene ENSG00000109743.
Subcellular location: Cell membrane
Pathways (Reactome):
Immune System: Neutrophil degranulation
Metabolism: Nicotinate metabolism
Metabolism of proteins: Post-translational modification: synthesis of GPI-anchored proteins
Gene Ontology:
Molecular function: NAD+ nucleosidase activity, cyclic ADP-ribose generating; hydrolase activity, acting on glycosyl bonds
Biological process: positive regulation of cell population proliferation; regulation of actin cytoskeleton organization; regulation of calcium-mediated signaling; regulation of cell-matrix adhesion; regulation of inflammatory response; regulation of neutrophil chemotaxis; humoral immune response; regulation of cellular extravasation; regulation of integrin-mediated signaling pathway; regulation of superoxide metabolic process; signal transduction
Cellular component: extracellular exosome; plasma membrane; uropod; extracellular region; specific granule membrane; membrane
Genetic constraint (gnomAD): Loss-of-function variants: 43 observed, 33.82 expected, observed/expected ratio (o/e) 1.27, 90% interval 1 to 1.64. The upper end of that interval is the gene's LOEUF score, 1.64, which puts it in group 6 of 6, group 1 being the genes least tolerant of losing a copy. Missense variants: 421 observed, 380 expected, observed/expected ratio (o/e) 1.11, 90% interval 1.02 to 1.2. Synonymous variants: 157 observed, 145.65 expected, observed/expected ratio (o/e) 1.08, 90% interval 0.95 to 1.23.
Homologues: Orthologues: chimpanzee BST1 (97% identical), macaque BST1 (92% identical), dog BST1 (75% identical), pig BST1 (75% identical), rabbit BST1 (73% identical), rat Bst1 (73% identical), mouse Bst1 (70% identical). Paralogues in human: CD38 (32% identical).
Diseases named in the same sentence as BST1 in open-access papers:
BST1 is named in the same sentence as 83 diseases in open-access papers, as found by Europe PMC text mining. Sharing a sentence is not in itself a finding about the gene and the disease. The quoted sentences say what the papers report.
Anxiety (24 papers, 2014 to 2025). Intense feelings of nervousness, tension, or panic often arise in response to interpersonal stresses. "In addition, we have recently demonstrated that mice deficient in the CD157/BST1 gene exhibited anxiety-related and depression-like behaviors." (PMID 26010484, 2015). "On the other hand, BST1 knockout mice showed anxiety and depression-like behaviors when compared to wild-type mice." (PMID 35806906, 2022). "Other functions of Bst1 such as its roles in humoral immune response, regulation of intestinal homeostasis, regulation of behaviors related with depression and anxiety have been revealed." (PMID 36267620, 2022). "After knocking out the BST1, the BST1−/− male mice exhibited anxiety-related and depression-like behaviors compared with wild-type mice." (PMID 35870967, 2022). "Another group demonstrated that BST1 KO mice exhibited social deficits and anxiety-like behaviors, which were rescued by administration of NR60." (PMID 34799586, 2021). "In contrast, decreased BST1 in LongC may entail decreased neurogenesis in the hippocampus, which controls emotions, such as anxiety and depression, in addition to memory and learning." (PMID 38612641, 2024). "CD157/BST-1 is a glycosyl phosphatidylinositol-anchored membrane protein that functions as an ADP ribosyl cyclase, and the loss of CD157 expression in mice results in anxiety-like behaviors and social behavioral deficits." (PMID 39275136, 2024). "Besides, experiments demonstrated that compared with wild-type mice, BST1 knockout (BST1–/–) mice exhibited anxiety-related symptoms, depression-like behaviors, and impaired social interaction similar to those observed in PD patients, suggesting a potential role of BST1 in pre-motor symptoms of PD." (PMID 40308892, 2025). "The relevance of BST‐1 to disease states has not been extensively explored, but it has been reported that BST1 KO mice exhibit social deficits and anxiety‐like behaviors, which are rescued by the administration of NR." (PMID 37424179, 2024).
Parkinson disease (24 papers, 2012 to 2025). A progressive degenerative disorder of the central nervous system characterized by loss of dopamine producing neurons in the substantia nigra and the presence of Lewy bodies in the substantia nigra and locus coeruleus. "Two trimodal QTLs (rs4389574 and rs4698412) were associated with Parkinson’s disease and implicated bone marrow stromal cell antigen 1 (BST1, 21–28 kb away), which has a known role in humoral inflammatory response." (PMID 39870618, 2025). "As above, SNPs in the BST-1/CD157 gene have been reported to be associated with at least five different neuropsychiatric diseases: Parkinson’s disease, ASD, iBRD, MDD and RLS." (PMID 37313401, 2023). "Bst1 has been associated with diseases, such as ovarian cancer, Parkinson’s disease, and rheumatoid arthritis." (PMID 36267620, 2022). "Nevertheless, the BST–1/CD157 gene (which codes for CD157) has recently been associated with Parkinson’s disease." (PMID 34198948, 2021). "Single-nucleotide polymorphisms of the CD38 and CD157/BST1 genes are associated with multiple neurological and psychiatric conditions, including autism spectrum disorder, Parkinson’s disease, and schizophrenia." (PMID 31881755, 2019). "GWASs and meta-analyses for Parkinson’s disease identified intronic SNPs in the CD157/BST1 gene as new susceptibility loci in Asian and European populations." (PMID 31881755, 2019). "Some of these genes and loci were previously discussed in relation to diseases and other molecular QTL studies, such as BST1, a gene known to be implicated in Parkinson’s Disease." (PMID 28129359, 2017). "Previous studies have reported associations between single-nucleotide polymorphisms (SNPs) of the CD157/BST1 gene with Parkinson’s disease." (PMID 26010484, 2015). "CD157 was first isolated as bone marrow stromal cell antigen-1, and later, several single nucleotide polymorphisms (SNPs) of the CD157 gene were reported to be associated with Parkinson’s disease." (PMID 25612002, 2015). "Recent genetic analysis identified the CD157/BST1 gene on human chromosome 4p15 as a susceptibility marker for Parkinson’s disease." (PMID 26010484, 2015). "Although CD157/Bst1 is a risk locus in Parkinson's disease (PD), little is known about the function of CD157 in the nervous system and contribution to PD progression." (PMID 24795584, 2014). "Parkinson’s disease-associated SNPs tested in the BST-1/CD157 gene." (PMID 37313401, 2023). "An exciting study was reported in 2009 that genome-wide association studies (GWASs) identified single-nucleotide polymorphisms (SNPs) in the CD157/BST1 gene as risk factors for Parkinson’s disease in the Japanese cohort, followed by confirmation in different populations in subsequent reports." (PMID 31881755, 2019). "BST1, recently reported to be part of a risk locus for Parkinson’s disease via genome-wide association study, might be another interesting target due to its role in B cell growth regulation." (PMID 23737949, 2013). "Of the other SNPs that predicted outcomes at p<10−5, rs10516292, an intergenic SNP approximately 16 kb from BST1 stands out for its potential relevance to neurodevelopment and neuroresiliency, due to numerous independent studies and meta-analyses associating BST1 variants and Parkinson’s disease." (PMID 23049896, 2012). "Moreover, CD157/BST-1 is associated with neuropsychiatric disorders, such as Parkinson’s disease, autism spectrum disorder (ASD), rapid eye movement sleep behavior disorder, major depressive disorder, restless leg syndrome/Willis–Ekbom disease, and Alzheimer’s disease." (PMID 39275136, 2024). "Although little is known about the physiological roles of CD157 in the brain, or the context of brain degeneration in Parkinson’s disease, an association between the CD157/BST1 gene and ASD has been reported." (PMID 35215455, 2022).
Parkinson disease (continued). "Recent rodent and human studies provide evidence in support of the fact that CD157, well known as bone marrow stromal cell antigen-1 (BST-1) and a risk factor in Parkinson’s disease, also meaningfully acts in the brain as a neuroregulator and affects social behaviors." (PMID 28340569, 2017). "The most robust and consistent longitudinal predictors of cognitive function included older age, baseline Unified Parkinson’s Disease Rating Scale (UPDRS) parts I and II, Schwab and England activities of daily living scale, striatal dopamine transporter binding, and SNP rs11724635 in the gene BST1." (PMID 28604798, 2017). "It is tempting to postulate that, during early brain development, CD157/BST-1 expression is under FOXP2-mediated transcriptional control, which may not involve the region containing Parkinson disease-associated SNPs." (PMID 26010484, 2015).
depression (18 papers, 2014 to 2025). "Gender subgroup analyses found that BST1 was correlated with neuroticism score in male CSF (r = − 0.011, P = 1.80 × 10− 5), while CNTN2 was correlated with depression score in female brain (r = − 0.013, P = 6.43 × 10− 4)." (PMID 35870967, 2022).
ovarian carcinoma (13 papers, 2012 to 2025). A malignant neoplasm originating from the surface ovarian epithelium. "These include AIF1, CD8A, and BST1 in ovarian cancer BRCA1-mutant cancers, and SEC61A2 and IGFBP3 in BRCA2-mutant ovarian cancer." (PMID 40647506, 2025). "CD157 (bst-1, bone marrow stromal antigen-1) is a cell surface molecule expressed in myeloid, endothelial, mesothelial, and epithelial ovarian cancer cells, and acts as an ectoenzyme and a signaling receptor." (PMID 34001228, 2021). "It has been also demonstrated that BST-1/CD157 is involved in the progression and differentiation of leukemia, metastasis of ovarian carcinoma cells, malignant mesothelioma and glioma, and thus could be used as diagnostic or prognostic markers." (PMID 37313401, 2023). "CD157/BST-1 is also involved in the pathogenesis of various diseases, such as the survival of B lymphocytes in rheumatoid arthritis, the progression of leukemia, and metastasis of human ovarian carcinoma cells." (PMID 26010484, 2015). "In ovarian cancer, BRCA1-mut cancer genes such as AIF1, CD8A, and BST1 showed detrimental prognosis, while in BRCA2-mut ovarian cancer, SEC61A2 and IGFBP3 were associated with shorter survival." (PMID 40647506, 2025). "CD157/BST-1 exhibits the same dualism of properties as CD38 like receptor and enzyme activity in leukocytes and ovarian cancer cells, bone marrow stromal cells, myeloid cells, and netrophils and hematopoietic stem cells." (PMID 33304350, 2020). "CD157/BST-1 is also involved in the pathogenesis of several diseases such as survival of B lymphocytes in rheumatoid arthritis, progression of leukemia, and metastasis of human ovarian carcinoma cells." (PMID 28515684, 2017).
rheumatoid arthritis (9 papers, 2014 to 2025). A chronic, systemic autoimmune disorder characterized by inflammation in the synovial membranes and articular surfaces. "BST1 has been implicated in other autoimmune conditions such as rheumatoid arthritis and certain malignancies suggesting shared inflammatory pathways." (PMID 40918143, 2025). "BST1 expression is enhanced in bone marrow stromal cell lines derived from patients with rheumatoid arthritis." (PMID 28129359, 2017). "CD157, discovered as bone marrow stromal cell antigen-1 (BST-1) by Hirano and colleagues, is a cell-surface molecule that supports pre-B cell growth with enhanced expression on bone marrow stromal cell lines derived from rheumatoid arthritis patients." (PMID 28340569, 2017). "Bone marrow stromal cell antigen-1 (BST-1) was first isolated as a cell surface molecule that supports the pre-B cell growth with enhanced expression on the bone marrow stromal cell lines derived from rheumatoid arthritis patients." (PMID 24795584, 2014). "Nurse-like cells cloned from bone marrow and synovial tissues of patients with rheumatoid arthritis promoted survival of peripheral B cells, which was significantly blocked by anti-BST-1/CD157 antibody; and recombinant soluble BST-1/CD157 showed a similar survival effect." (PMID 37313401, 2023).
autism spectrum disorder (7 papers, 2015 to 2024). A spectrum of developmental disorders that includes autism, and Asperger syndrome. "And additionally, we cannot exclude the possibility that psychiatric phenotypes in CD157 KO mice are related to autism spectrum disorder (ASD), because it was reported that CD157/BST1 SNPs showed significant association with ASD." (PMID 28515684, 2017). "It has been shown that social behaviors are impaired in CD157 knockout mice without severe motor dysfunction and that CD157/BST1 gene single nucleotide polymorphisms are associated with autism spectrum disorder in humans." (PMID 28340569, 2017).
acute myeloid leukemia (6 papers, 2017 to 2023). Acute myeloid leukemia (AML) is a group of neoplasms arising from precursor cells committed to the myeloid cell-line differentiation. "Particularly, BST-1/CD157 has been regarded as a target for immunotherapy of acute myeloid leukemia." (PMID 37313401, 2023). "CD157/BST-1 (a member of the ADP-ribosyl cyclase family) is expressed at variable levels in 97% of patients with acute myeloid leukemia (AML), and is currently under investigation as a target for antibody-based immunotherapy." (PMID 34707185, 2021).
malignant pleural mesothelioma (4 papers, 2014 to 2024). A malignant neoplasm that arises from mesothelial cells in the pleura and shows a diffuse growth pattern. "CD157/Bst1 glycoprotein is expressed in >85% of malignant pleural mesotheliomas and is a marker of enhanced tumor aggressiveness." (PMID 29854315, 2018).
Sepsis (3 papers, 2020 to 2026). Sepsis is defined as life-threatening organ dysfunction caused by a dysregulated host response to infection. "In addition, there was association with FGF13 through BST1 and PCOLCE2 through SH3GLB1 in pediatric sepsis." (PMID 32318053, 2020).
asthma (2 papers, 2015 to 2017). "In a study on two young sisters with ASD, a deletion of 4p15.32, resulting in a BST1 (bone marrow stromal cell antigen 1)—CD38 fusion transcript and in disruption of CD38 expression, was identified only in the girl affected by more severe ASD and asthma." (PMID 28848387, 2017).
cavernomas (2 papers, 2019 to 2020). "Colocalization of Bst1 and the cavernoma transcripts Klf2, Klf4, and Ly6a using Visium showed concentration of Bst1 progenitor cell transcripts at the level of cavernomas and mulberry lesions." (PMID 33138917, 2020).
glioma (2 papers, 2023). A benign or malignant brain and spinal cord tumor that arises from glial cells (astrocytes, oligodendrocytes, ependymal cells). "Most importantly, it proved that CD38, NMNAT2, PARP9, and BST1 might be important prognostic molecular markers and potential therapeutic targets for glioma patients." (PMID 36778644, 2023). "However, to the best of our knowledge, BST1 and NMNAT2 were found to be closely associated with glioma for the first time." (PMID 36778644, 2023). "The four genes, PARP9, BST1, NMNAT2, and CD38, might be important molecular biomarkers and therapeutic targets for glioma patients." (PMID 36778644, 2023).
Hyperglycemia (2 papers, 2008 to 2025). An increased concentration of glucose in the blood. "Several interferon-stimulated genes (Bst1, Ifit1bl2, Ifih1) were also upregulated, indicating that B12 restored interferon responsiveness, which is often impaired under hyperglycemia." (PMID 41463345, 2025).
lung carcinoma (2 papers, 2015 to 2018). "Among genes that are suppressed, there are a number involved in the immune response, including CD177 and BST1, suggesting an impaired immune response in the airway of smokers with lung cancer." (PMID 25944280, 2015).
viral infections (2 papers, 2014 to 2024). "Furthermore, the use of BST1 knockout mice to study HIV or SARS-CoV-2 infection may elucidate not only the neurological consequences of these viral infections but also validate BST1 as a therapeutic target for these diseases." (PMID 38612641, 2024).
autoimmune disease (1 paper, 2023). A disorder resulting from loss of function or tissue destruction of an organ or multiple organs, arising from humoral or cellular immune responses of the individual to their own tissue constituents. "More importantly, BST-1/CD157 holds much pathogenetic and clinical significance in various diseases including autoimmune diseases, hematologic malignancies and solid tumors." (PMID 37313401, 2023).
Burkitt lymphoma (1 paper, 2017). A rare form of malignant mature B-cell non-Hodgkin lymphoma. "BST1-001 transcript was detected in all samples examined here except for Raji Burkitt’s lymphoma cell line whereas the BST1-002 transcript containing exon 1b was most evident in PMN, fetal and adult brain, cerebellum and colon." (PMID 29162908, 2017).
chronic lung allograft dysfunction (1 paper, 2022). Chronic lung allograft dysfunction encompasses a range of pathologies that cause a transplanted lung to not achieve or maintain normal function. "A study shows that BST1 could be used as biomarkers of chronic lung allograft dysfunction (CLAD) in bronchoalveolar lavage (BAL)." (PMID 35475279, 2022).
colorectal carcinoma (1 paper, 2016). A malignant epithelial neoplasm that arises from the colon or rectum and invades through the muscularis mucosa into the submucosa. "In the adherence assay, we found a significantly lower adherence, following a 60 minutes interaction period, of bst1Δ/Δ to KB (derived from a buccal carcinoma) and Caco-2 (derived from a colorectal carcinoma) monolayers as compared to the parent and BST1-complemented strains." (PMID 27708385, 2016).
developmental delay (1 paper, 2017). "Thus, the aim of our present study was to investigate the effect of Cd157/Bst1 gene deletion on developmental aspects of vocal communication ability to determine if ASD-related communication deficits are due to a general impairment or developmental delay." (PMID 28566999, 2017).
disseminated candidiasis (1 paper, 2016). Systemic candidiasis occurs when Candida yeast enters the bloodstream and may spread (becoming disseminated candidiasis) to other organs, including the central nervous system, kidneys, liver, bones, muscles, joints, spleen, or eyes. "Therefore, we investigated the contribution of BST1 to the development of hematogenously disseminated candidiasis in a mouse model." (PMID 27708385, 2016).